ENSG00000262660 (novel protein)
Gene: Protein-coding gene on chromosome 17 (81,703,371 to 81,720,539, forward strand). Ensembl gene ENSG00000262660.
Genetic constraint (gnomAD): Loss-of-function variants: 39 observed, 54.87 expected, observed/expected ratio (o/e) 0.71, 90% interval 0.55 to 0.93. Missense variants: 583 observed, 606.22 expected, observed/expected ratio (o/e) 0.96, 90% interval 0.9 to 1.03. Synonymous variants: 266 observed, 253.22 expected, observed/expected ratio (o/e) 1.05, 90% interval 0.95 to 1.16.